RNU6-1138P (RNA, U6 small nuclear 1138, pseudogene)
Gene: Small nuclear RNA gene on chromosome 14 (23,156,309 to 23,156,414, reverse strand). Ensembl gene ENSG00000202229.
Homologues: Orthologues: chimpanzee U6 (98% identical), macaque U6 (91% identical), guinea pig U6 (83% identical), dog U6 (79% identical), dog U6 (74% identical). Paralogues in human: RNU6-43P (86% identical), RNU6-727P (85% identical), RNU6-1274P (84% identical), RNU6-1011P (83% identical), RNU6-1127P (83% identical), RNU6-1216P (83% identical), RNU6-242P (83% identical), RNU6-24P (83% identical), RNU6-517P (83% identical), RNU6-589P (83% identical), RNU6-761P (83% identical), RNU6-1091P (82% identical), and 1289 more.